RNU5F-3P (RNA, U5F small nuclear 3, pseudogene)
Gene: Small nuclear RNA gene on chromosome 18 (6,017,723 to 6,017,839, reverse strand). Ensembl gene ENSG00000200637.
Homologues: Orthologues: chimpanzee U5 (98% identical), macaque U5 (93% identical). Paralogues in human: RNU5F-7P (81% identical), RNU5E-7P (76% identical), RNU5F-8P (75% identical), RNU5B-4P (74% identical), RNU5E-4P (74% identical), RNU5A-7P (73% identical), RNU5E-10P (73% identical), RNU5E-8P (73% identical), RNU5F-6P (73% identical), RNU5E-6P (70% identical), RNU5A-4P (69% identical), RNU5A-6P (69% identical), and 13 more.